CCL2 (C-C motif chemokine ligand 2)
Diseases named in the same sentence as CCL2 in open-access papers (continued):
Sharing a sentence is not in itself a finding about the gene and the disease.
COVID-19 (continued). "We observed CCL2 and IL-6 overexpression in both severe and moderate COVID-19 groups that exceeded thousands of folds compared to controls, and these elevations were significantly higher in the severe COVID-19 group than in the moderate group." (PMID 35982898, 2022). "The authors thus suggested that both miRNAs, along with enhanced lncRNA levels, may promote IL-6R/CCL2 translation in COVID-19 patients, contributing to IL-6-induced cytokine storms." (PMID 35207576, 2022). "However, one meta-analysis found that severe cases of COVID-19 had greater levels of chemokines (CCL2 and CCL11) than moderate ones." (PMID 35958594, 2022). "Similarly, CCL2 was significantly increased in post-COVID-19 BAL, and tightly correlated to BAL monocyte numbers." (PMID 35151371, 2022). "CCL2, CXCL10, and CXCL8 are the most commonly found chemokines associated with COVID-19 severity." (PMID 35782361, 2022). "Therefore, the current study aimed to investigate lncRNAs, particularly NEAT1 and TUG1, and their association with IL-6, CCL2, and TNF-α in COVID-19 patients with moderate and severe disease." (PMID 35982898, 2022). "The novel coronavirus SARS-CoV-2 binds to human angiotensin-converting enzyme II (ACE2) through its expressed S-protein and enters the cell, while ACE2 activates the expression of CCL2, and studies have also shown that the pathogenesis of COVID-19 is closely related to the excessive release of CCL2." (PMID 35726234, 2022). "Of note, Ccl8 and Ccl2 as well as Cxcl9 and Cxcl10, chemoattractants for monocytes and T cells, respectively, were significantly up-regulated in the lungs of AR-infected mice and in COVID-19 patients, in line with the increased recruitment of these cells." (PMID 34812647, 2022). "Moreover, increased CCL2 levels were reported to be correlated with the development of acute kidney injury in critically ill COVID-19 patients, and patients with higher CCL2 expression tend to have detrimental disease progression." (PMID 35464491, 2022). "Bronchoalveolar lavage (BAL) from COVID-19 patients show upregulated: a) chemokine genes such as CCL2 and CXCL8, which function as chemoattractants for inflammatory monocytes and neutrophils, respectively, and b) classical pro-inflammatory cytokine genes such as IL1RN and IL1B." (PMID 33596401, 2021). "Post-mortem COVID-19 lung samples also display strong induction of a subset of ISGs, particularly monocyte associated chemokines such as CCL2/MCP-1 and CCL8/MCP-2, yet without detectable expression of IFN-I or IFN-III." (PMID 34239884, 2021). "Indeed, corticosteroids have been shown to suppress CRS, and NR3C1 has been shown to transcriptionally downregulate many inflammatory cytokines overexpressed in COVID-19 patients, such as CCL2, IL1B, and IL6." (PMID 34163359, 2021). "COVID-19 patients who succumb to pneumonia and hypoxia had one hallmark feature of the profound inflammatory state that marked elevation of serum inflammatory cytokines (IL-6, IFN-γ, IL-1β, TNF-α and TGF-β) and chemokines (CCL2, CCL5, CXCL8 and CXCL10)." (PMID 34313585, 2021). "Recent research has also identified that the synergism of TNF-α and IFN-γ can trigger inflammatory cell death, tissue damage, and mortality in SARS-CoV-2 infection, and shown increased levels of IFN-γ, TNF-α, CXCL10, and CCL2 in the serum of severe COVID-19 patients." (PMID 33879239, 2021). "A single-cell study of bronchoalveolar lavage fluid (BALF) in intubated COVID-19 patients identified two inflammatory macrophage subsets—one characterized by CCL2, CCL3, and CXCL10 expression and a second by FCN1 and S100A8—as potential mediators of pathology in this late-stage disease." (PMID 33879239, 2021). "In particular, we have identified a CXCL10+ CCL2+ inflammatory macrophage phenotype shared between tissues affected in autoimmune disease (RA), inflammatory diseases (CD and UC), and infectious disease (COVID-19)." (PMID 33879239, 2021).
COVID-19 (continued). "Furthermore, recent lung autopsy findings have suggested that seriously ill patients with COVID-19 have considerably higher levels of a set of chemokines, including CCL2, CXCL5, and CXCL6, than moderately ill patients." (PMID 33946736, 2021). "One study also found that MCP-1/CCL2 elevation positively correlated with mortality from COVID-19." (PMID 34575258, 2021). "We found that statins may be effective by ameliorating endothelial dysfunction triggered by cytokine storm cytokines/chemokines (IL-6, TNF-α, IL-1β, CCL2, interferons, and related factors) released from COVID-19 patients." (PMID 34253708, 2021). "Actually, lung inflammation caused by COVID-19 can be aggravated because of macrophage activation syndrome and its production of several inflammatory cytokines (IL-6, IL-7, TNF), chemokines (CCL2, CCL3, CXCL10) and the soluble form of α-chain of the IL-2 receptor." (PMID 33859644, 2021). "Abnormal upregulation of CCL2 results in sustained and exacerbated cell recruitment and uncontrolled inflammation, as seen in rheumatoid arthritis, atherosclerosis, diabetes and COVID-19, among others." (PMID 33923693, 2021). "Moreover, the fatality rate was found positively correlated with CXCL10 and CCL2 critically ill patients with COVID-19." (PMID 33946736, 2021). "The present study hypothesizes that SARS-CoV-2 infection can produce alterations in the expression of PON1, CCL2, and galectin-3, which may be involved in the pathophysiology of COVID-19." (PMID 34205807, 2021). "Cytokine storm is hypercytokinemia that increases the volume of pro-inflammatory cytokines in the serum (e.g. IL-1β, IL-6, IL-12, INF-γ) and chemokines (CXCL10 and CCL2), and is correlated with pulmonary inflammation and extensive lung involvement as seen in COVID-19 patients." (PMID 33205807, 2020). "PBMCs derived from COVID-19 patients and stimulated in vitro showed an increase in expression of CCL2, CXCL10, Eotaxin, and IL-1RA, and stimulation of CD8+ T cells were associated with an increase in IFN-γ levels, which indicates the functional responsiveness of these cells." (PMID 33335518, 2020). "Elevated levels of TNF-α, CXCL10, CCL2, and IL-10 in COVID-19 patients correlate with reduced populations of specific intestinal bacterial, which suggests that gut dysbiosis may contribute significantly to the development of intense and widespread inflammation." (PMID 38701071, 2024). "However, in COVID-19 patients, a decrease in miR-451a expression coupled with its binding to lncRNAs could amplify IL-6R/CCL2 expression at the protein level." (PMID 38140218, 2023). "It was shown that targets of the drug combinations (including TNF, IL1B, IL10, and CCL2) (p=5.72×10−5) and, specifically, its individual drugs including EH (p = 0.00142), PR (p=4.37×10−4), and GR (p=5.81×10−5) are significantly overlapped with COVID-19-related genes obtained from the CTD database." (PMID 36611603, 2023). "Patients with severe COVID-19 exhibit higher levels of pro-inflammatory cytokines (such as IL-6 and IL-8) in their bronchoalveolar lavage fluid as well as increased expression of inflammatory chemokines (such as CCL2) in macrophages compared to those with mild COVID-19." (PMID 36992366, 2023). "Indeed, the bronchoalveolar fluid (BALF) of severe COVID-19 patients contains high concentrations of CCL2, CCL3, CCL4, and CCL7, and a decreased proportion of tissue-resident alveolar macrophages, but high amounts of inflammatory monocyte-derived macrophages (Liao and others 2020)." (PMID 35647937, 2022). "Studies focusing on single-cell RNA sequencing of COVID-19 patient bronchoalveolar lavage fluid pointed out that macrophage subsets producing CCL2 and CXCL10 are abundant in the bronchoalveolar lavage fluid from severe COVID-9 patients and might be potential mediators in the COVID-19 disease." (PMID 36451835, 2022).
COVID-19 (continued). "Furthermore, we identified significant positive correlations between NEAT1 and CCL2, and IL-6, which may explain its pathological role in COVID-19 by targeting CCL2 and IL-6 and increasing their production, specifically in the severe form of the disease." (PMID 35982898, 2022). "Taken together, our findings suggest that admission values of lymphocyte counts, neutrophil-to-lymphocyte ratio and the levels of some inflammatory markers (IL8/CXCL8, MCP-1/CCL2, IL-10, and C-reactive protein) may be useful as COVID-19 outcome predictors during hospitalization." (PMID 36035415, 2022). "COVID-19 patients have high levels of proinflammatory cytokines, including interleukin (IL)-1β, IL-6, IL-8, interferon-gamma (IFNγ), 10 kD interferon-gamma-inducible protein (IP-10), and monocyte chemoattractant protein-1 (MCP-1, CCL-2), which probably activate T-helper-1 (Th1) cell responses." (PMID 36294868, 2022). "These miRNAs target several pro-inflammatory cytokine and chemokine genes (e.g., TNF, CCL2, CXCL9, CXCL10, IL10, VEGFA) as well as cytokine and chemokine receptors and transduction factors (IL1R1, IL2RA, IFNAR2), reported as upregulated and associated with mortality in COVID-19 patients." (PMID 36032130, 2022). "Additionally, our data further support the hypothesis of dysregulation of mononuclear phagocytes, as CCL2, increased in COVID-19, promotes macrophage migration and differentiation." (PMID 35386707, 2022). "We found that similar to monocytes CCR2 and CXCR3 were upregulated in DC3 of COVID-19 patients suggesting that DC3 together with monocytes may be recruited from the circulation to the infected lung in response to a gradient of CCL2 and CXCR3 ligands CXCL9/10/11." (PMID 34614036, 2021). "This study emphasizes that biologically active components of spices might alleviate the sustained pro-inflammatory condition by inhibiting the activity of tumor necrosis factor-alpha (TNF-α), interleukins (IL6, IL8), and chemokine (CCL2) known to be elevated in COVID-19." (PMID 34513735, 2021). "Notably, we observed a significant correlation between the cross-disease shared CXCL10+ CCL2+ macrophages and two monocyte-derived alveolar macrophage (MoAM) inflammatory phenotypes from this independent severe COVID-19 cohort (wherein they were referred to as MoAM1 and MoAM2)." (PMID 33879239, 2021). "Interestingly, the listed genes reported as potent markers of critical illness in COVID-19 (CCL2, MMP8, IFI44, LCN2, SAA1) were identified by us as key regulators of both murine ALI and COVID-19-associated ARDS in human with the highest scores of degree centrality." (PMID 34807957, 2021). "Likewise, higher levels of CCL2, CCL7, CCL20, and CXCL10 were associated with lower blood lymphocyte count and higher inflammatory markers (CRP and ferritin), which are clinical markers of severe disease and poorer outcome in COVID-19." (PMID 33704068, 2021). "The aim of this work was to evaluate the associations of polymorphisms in the TNF-α, IL-6, IL-8, IL-10, CCL5 and CXCL6 genes with COVID-19 outcomes and with the serum levels of IFN-α, IFN-γ, TNF-α, IL-1Ra, IL-6, IL-7, IL-10, CCL2, CCL3, CXCL8, CXCL10 and GCSF." (PMID 40881695, 2025). "In COVID-19, severe outcomes have increased levels of pro-inflammatory and anti-inflammatory cytokines and chemokines, such as IL-6, TNF-α, IL-10, CCL2, CCL3, CXCL8, and CXCL10, among others." (PMID 40881695, 2025). "In the context of COVID-19, chemokines such as CCL2 (MCP-1) and CXCL10 (IP-10) have been identified as key players in mediating immune cell migration and activation, which are crucial in the development and persistence of inflammation." (PMID 40094929, 2025). "The analysis of cord blood samples at Early and Intermediate convalescent COVID-19 showed increased levels of CCL11, CCL3, CCL4, CCL2, IL-1β, IFN-γ, IL1-Ra, G-CSF, and IL-7 and a decrease of IL-10 and IL-2 as compared with HC." (PMID 40821818, 2025).
COVID-19 (continued). "Multiple studies show high levels of proinflammatory cytokines such as IL-1, TNF, IFNs, IL-6, IL-8, IL-18, IL-17α, G-CSF, and GM-CSF, as well as chemokines, such as MCP-1, IP-10, MIP-1α, CXCL10, CCL2, CCL4, CCL14, CCL19, and CCL25 in severe cases of COVID-19." (PMID 40076291, 2025). "Inflammatory cytokines and chemokines, including IL-1, IL-6, IL-8, IL-17, CCL-2, TNF-α, G-CSF, IP-10, MCP-1 and MIP, are elevated in COVID-19 patients." (PMID 40794529, 2025). "A recent study observed significant overexpression of NEAT1 in the blood of COVID-19 patients and found that NEAT1 is significantly correlated with cytokines such as IL-6, CCL2, and TNF-α." (PMID 40285022, 2025). "The main inflammatory cytokines and chemokines widely produced by patients with severe forms of COVID-19 are IL-6, IL-8, IL-1β, TNF-alpha, IFN-gamma, MIP1α and 1β, CCL2, CCL5, CCL20, CXCL1, CXCL2, CXCL8, CXCL10, and CXCL17." (PMID 39768136, 2024). "Some chemokines were also elevated in patients with severe COVID-19, as chemokine ligand (CCL)-2 (CCL2), CCL3, and chemokine CXC ligands (CXCL), CXCL8, CXCL9, CXCL10, and CXCL11 the most associated with this clinical condition." (PMID 39281667, 2024). "In one study, it was noted that the activation of the innate immune system and cytokine storms (featuring elevated levels of TNF, IL-6, CXCL10, CCL2, CCL5, and IFN2) play crucial roles in the pathogenesis of COVID-19." (PMID 39685844, 2024). "Five chemokines were explored in this study, where 3 of them (MCP-1/CCL2, IL-8/CXCL8, and IP-10/CXCL10) showed a significant increase in COVID-19 patients with further increase in higher severities." (PMID 38855114, 2024). "Evidence suggests that an involvement of CCL2 and its receptor (CCR2) is involved in the collection of monocytes and the infusion of these cells into the lungs of COVID-19 patients." (PMID 38803488, 2024). "On the other hand, CCL2 and CXCL10, elevated in severe cases, highlight the importance of chemokines in mediating immune responses and exacerbating lung injury in COVID-19." (PMID 39203987, 2024). "Expanding upon the significance of chemokines such as CCL2 and CXCL10 in severe COVID-19 cases, it is critical to understand their function in orchestrating the immune response, especially in lung injury and systemic inflammation." (PMID 39203987, 2024). "Using age-based stratification analysis in adjusted genetic models, the interaction of CCL2, OAS1, and DPP9 SNVs with the presence of the severe COVID-19 phenotype was examined." (PMID 38694517, 2024). "Among the many cytokines with significantly greater cumulative exposure in COVID-19 were CXCL10, CCL8, CCL2, IL-6, and TNF-α (q < 0.05, Mann-Whitney)." (PMID 38502186, 2024). "Genotyping for gene variants at rs1024611 (A>G), rs10774671 (A>G), and rs10406145 (G>C) of CCL2, OAS1, and DPP9 genes was performed on 100 COVID-19 patients (43 with severe form and 57 asymptomatic-mild) using RFLP-PCR." (PMID 38694517, 2024). "Several cytokines (GM-CSF and IL-6) and chemokines (MCP-1/CCL2, IL-8/CXCL8, and IP-10/CXCL10) were markedly increased in COVID-19 patients with a significant correlation with disease severity." (PMID 38855114, 2024). "Cytokine profiling of the sera of patients with COVID-19 and the transcriptional analysis of their BAL fluid revealed increased IL-6, G-CSF, CXCL10, CCL2, CCL3, and TNF-α levels, correlating with disease severity and progression." (PMID 39417078, 2024). "Pyroptosis was found in COVID-19 patients with increases of IL-1β and IL-18, which further promoted the secretion of pro-inflammatory cytokines such as IL-6, IFN-γ, MCP-1/CCL2, MIP-1α/CCL3, MIP-1β/CCL4." (PMID 37631016, 2023). "The study also measured proinflammatory cytokines and chemokines in the semen, including IL-6, tumor-necrosis-factor (TNF), and CCL2 (MCP-1), and COVID-19 patients had significantly higher levels than the control group." (PMID 37457430, 2023).
COVID-19 (continued). "Among the modified genes, CCL2, CCL7, and CCL8 were increased in post-COVID-19 monocytes, similar to levels in monocytes from patients with severe acute forms of COVID-19." (PMID 38203577, 2023). "Further, the expression of genes involved in endothelial dysfunction, namely CCL2, PDGFRA, PDGFB, and PDGFC, is found to be increased in ACE2-positive brain cells of COVID-19 patients." (PMID 37239234, 2023). "Other studies have also indicated severity associated with increased levels of plasma chemokines, such as CCL2, CXCL8, and CXCL10, in severe COVID-19." (PMID 37632046, 2023). "In severe conditions of COVID-19, there is a high abundance of CXCL10+ and CCL2+ inflammatory macrophages that heavily express the GBP1 inflammatory gene." (PMID 38162574, 2023). "Serum CCL2, CCL3, CCL7, CXCL9, CXCL10, IL-1β and IL-1Ra levels increased in critical COVID-19 patients (n = 11) when compared to both severe COVID-19 patients (n = 25) and moderate COVID-19 patients (n = 14)." (PMID 36941580, 2023). "Patients infected with COVID-19 have high levels of IL-1β, IFN-γ, IP-10/CXCL10, and MCP-1/CCL2, leading to activated T-helper-1 (Th1) cell responses." (PMID 36851766, 2023). "In severe cases of COVID-19, multiple studies have indicated higher levels of IL-2, IL-6, IL-7, IL-10, CXCL10(IP-10), CCL2 (MCP-1), TNF-α, CCL3(MIP-1α), and G-CSF when compared to patients with mild and moderate infections." (PMID 37834246, 2023). "The most relevant cytokines that were significantly associated with acute respiratory distress syndrome (ARDS) by COVID-19 were: MCP-3, TNF-α, fractalkine/CX3CL1, M-CSF, and MCP-1/CCL2." (PMID 36851766, 2023). "Results showed that patients with COVID-19 who were admitted to intensive care units had higher concentrations of CXCL10, CCL2, and TNF-α compared to that in patients with milder infections." (PMID 37363730, 2023). "Compared with the control group, there was extensive cytokine/chemokine correlations centered on IL-17A, IL-10, IL-6, CCL2, CXCL8, CXCL9 and CXCL10 and fewer correlations with IL-1β in the COVID-19 patients at baseline." (PMID 37662953, 2023). "This framework releases large amounts of pro-inflammatory cytokines, as in COVID-19, including IL-6, TNF, IL-1β, IL-12, IL-17, IL-18, IP-10, IFN-γ, CCL2 and CCL5." (PMID 35843719, 2022). "They showed that IL-6, CCL2, CXCL8, CXCL9, and CXCL10/IP10 levels were higher in patients with MIS-C than in those with COVID-19." (PMID 35268506, 2022). "Seven out of the 16 known cytokine markers (including IL1A, IL1R1, CCL2, IL6, IL10, CXCL10, and VEGFA) were less pronounced in KD than in severe COVID-19 patients compared to FC and HC, respectively." (PMID 36159873, 2022). "In another clinical investigation, COVID-19 patients requiring ICU admission exhibited higher levels of CXCL10, CCL2, CCL3, and CCL7 compared to mildly infected patients." (PMID 36016187, 2022). "High levels of chemokines were also detected in severe forms of COVID-19: IFN-induced proteins-10 (IP-10/CXC-chemokine ligand 10 (CXCL10)), CXCL9, monocyte chemoattractant protein-1 (MCP1), chemokine ligand-2 (CCL)-2 and IL-8." (PMID 36560410, 2022). "Increase in inflammatory monocytes correlates with severity of disease, and recruitment is through chemokines CCL2 and CCL7, both of which elevated in fatal COVID-19 cases." (PMID 34468841, 2022). "Thus, CCL2 blockade may help to delay or reduce the “cytokine storm” in patients with COVID-19." (PMID 36005818, 2022). "MMP-7, TGF-β, CCL2, CCL-3, CXCL-10, G-CSF, IFN gamma, IL-10, IL-2, IL-4, IL-6, IL-7, TNF-α, IL-6, and IGF-1 were studied for their correlation to lung involvement in COVID-19 patients." (PMID 36286038, 2022). "We observed a reduction of CCL-2/MCP-1 and CXCL8/IL-8 peripheral levels after 12 weeks of supervised exercise in patients post-COVID-19." (PMID 36685603, 2022). "Our data also confirm the role of CCL2 and CXCL10 in severe COVID-19 as these chemokines were found to be increased in serum of patients admitted to ICU." (PMID 35386707, 2022).